GZMB (granzyme B)
Diseases named in the same sentence as GZMB in open-access papers (continued):
Sharing a sentence is not in itself a finding about the gene and the disease.
viral infection (83 papers, 2009 to 2025). "Granzyme B (GzmB) is a serine protease associated with various diseases like viral infections, autoimmunity, transplant rejection, and anti-tumor immunity." (PMID 38816839, 2024). "We have generated a novel mouse strain expressing a granzyme B variant found in wild mice (GzmBW), and exposed these mice to viral infections." (PMID 25502180, 2014). "Additionally, NK cell production of granzyme B, a protease that kills virus-infected cells, was diminished in il27rα-/- mice and associated with reduced viral clearance, suggesting a role of IL-27 in mediating NK cell effector functions during virus infection." (PMID 35634328, 2022). "More studies are needed to corroborate the findings that nearly all immune subsets express GzmB and further investigate the roles of GzmB during viral infection." (PMID 38814732, 2024). "Perforin and granzyme B protein play a role in the immune response to defence against virus infection and cancer." (PMID 39619199, 2024). "Resident NK cells acquire cytolytic functions mediated through TNFα and granzyme B during hepatotropic viral infections, cirrhotic pathology, and HCC (Sällberg and Pasetto, 2020)." (PMID 36656749, 2023). "In contrast, viral infection is characterized by a strong increase in type I interferons in affected tissues and these cytokines are well known to promote granzyme B production." (PMID 37520575, 2023). "(2012) demonstrated the essential role of granzyme B-producing Treg cells in controlling pulmonary inflammation during acute viral infection." (PMID 36969257, 2023). "During viral infection or inflammation, granzyme B is a potent killing factor produced by NK cells and CD8+ T cells." (PMID 36846163, 2023). "Granzyme B, which is a protease encoded by GZMB in cytotoxic lymphocytes (CTL) and NK cells, is implicated in virus infections and many autoimmune disorders including MG." (PMID 38384322, 2023). "Analysis of these markers in CD8+ Tnaive, TCM and TEFF cells showed that TCF1 was significantly reduced in endogenous TCM cells, and that GzmB expression was significantly reduced in all gBT.I cell subtypes after burn injury and viral infection." (PMID 35505970, 2022). "The role of GzmB in inducing a potent response is likely important for viral clearance, as previous studies have shown a role for granzymes in control of viral infections in humans, such as acute HIV." (PMID 35699447, 2022). "Further, CD4+ T cells also exert direct cytotoxicity through granzyme B and perforin release during viral infections." (PMID 36591284, 2022). "The following section portrays the relation between Gzms and the inflammatory in vitro and in vivo effects regarding viral infections for human GzmA, GzmB, GzmK, and GzmM." (PMID 34529743, 2021). "Viral infection also increased the expression of granzyme B+ in the spleen and peritoneal exudate NK cells; but this response was lower in the NK PEC of ICOS-KO mice." (PMID 31283790, 2019). "It is likely that detectable, albeit reduced, levels of antiviral GzmB+ T cells were sufficient to clear the viral infection given that a low dose of influenza virus (10 PFU) was used in our coinfection model." (PMID 31266877, 2019). "The dose-dependent induction of granzyme B expression in response to cytokine, or viral infection, is connected to the activation of the metabolic check-point kinase mTOR76." (PMID 30705279, 2019). "The survival time and survival rate of Kctd9-deficient mice were significantly improved, compared to that of the wild-type mice following virus infection, with less activated NK cells in Kctd9−/− mice evidenced by reduced Granzyme B and IFN-γ expression." (PMID 31024568, 2019). "Blood level of IFN-β, splenic IFN-γ and granzyme B-producing NK cells were lower in alcohol-consuming mice than in water-drinking mice at 12 hours after viral infection." (PMID 32123809, 2018).
viral infection (continued). "In viral infections, chronic stimulation leads to the loss of effector CD8+ T cells function by down-regulation of perforin and granzyme B expressions." (PMID 25605488, 2015). "Previous studies with viral infections have shown that granzyme B is predominantly secreted by CD8+ T cells, although, the contributions of NK cells and CD4+ cytotoxic cells have also been suggested." (PMID 25471494, 2014). "Out findings present the first evidence on the biological importance of the independent gzmB-inducible pro-apoptotic pathways in a physiological relevant virus infection model." (PMID 19838298, 2009). "In addition, IL‐2 produced by TRM cells in viral infection models has been shown to promote the upregulation of granzyme B (GZMB) in NK cells." (PMID 39802636, 2025). "Measurements of other key cytokines involved in T effector functions during viral infections, such as tumor necrosis factor alpha and granzyme B,24 might further validate the efficacy of the T-cell response observed in DS after primary SARS-CoV-2 vaccination." (PMID 41196011, 2025). "For example, CD8+ cytotoxic T lymphocytes (CTLs) among CD8+ T cells are an important component of cellular immunity in the fight against viral infection, and the main function of CTLs is to recognize and kill virus-infected cells by releasing perforin and granzyme B to induce apoptosis." (PMID 36249527, 2022). "We hypothesized that the virally associated BV01 signal we observed in vivo was due to increased recruitment of cells that produce GZMB in the lungs during viral infection." (PMID 35696579, 2022). "Finally, GzmB was suggested to affect the arrangement of membrane proteins anchored in the cytoskeleton, which has been related to viral infection, by cleaving the actin filament cross-linking protein filamin A." (PMID 34529743, 2021). "Granzyme B (GrB) is a cytolytic serine protease found in granules of innate immune effector cells (natural killer and cytotoxic T-lymphocyte cells), which functions to protect the body against viral infections and malignant cells." (PMID 33014289, 2020). "However, BALB/c mice induced significantly higher levels of granzyme B-secreting CD8 T cells than C57BL/6 mice at day 7 after viral infection." (PMID 29276514, 2017). "Importantly, we were unable to detect any signatures of an adaptive immune response, such as antiviral cytokine IFNγ or cytolytic molecules perforin and granzyme B, needed to clear viral infection and establish memory." (PMID 29123522, 2017). "Granzyme B+ CD8+-cells are effector cells in viral infections and cancer immunology." (PMID 22509265, 2012). "However, granzyme B levels, released by effector immune cells, were unaltered by virus infection." (PMID 37762490, 2023). "Therefore, we assessed the differentiation of effector CD4 and CD8 T cells in response to viral infection by analysis of production of effector cytokines and granzyme B. We discovered that Egr2 and 3 promoted clonal expansion but profoundly suppressed differentiation of effector CD4 and 8 T cells." (PMID 28487311, 2017). "Therefore, the development of the terminally differentiated CD8+ T cell, as represented by the expression of Blimp-1, can be separated from the acquisition of effector function, as has been recently emphasized by following the fate of cells that had expressed granzyme B during a viral infection." (PMID 21182077, 2011). "In Class1, the viral infection pathways (e.g., HSV-1, EBV) and antigen presentation (e.g., HLA-DRB1/DQB1/C, CD74, CTLA4, GZMB, PRF1) were primarily enriched." (PMID 41394852, 2025). "Since viral infections can affect the cytolytic granule production and cytotoxicity of CD8+ T cells, we evaluated the intracellular expression of perforin, granzyme A and granzyme B, along with the surface expression of CD107a molecule." (PMID 39764446, 2024).
viral infection (continued). "Compared to cluster 4, cluster 2 cells showed higher expression of SLAMF7, ZEB2, GZMB, GPR18, CD72, PDCD1 (PD1) and CRTAM that are known to be expressed in terminally differentiated effector cells in viral infections and various cancers." (PMID 38501302, 2024). "IFN‐I can activate the STAT3/4‐granzyme B pathway in tumor‐infiltrating CD8+ T cells, inhibit tumor growth, and directly maintain the clonal expansion of CD4 T cells to fight virus infection." (PMID 35253368, 2022). "However, Klebsiella pneumoniae is caused by a bacterium rather than a virus and as GZMB is mainly involved in the cell mediated cytotoxic immune response, it may be more effective in the elimination of viral infections and intracellular bacteria." (PMID 31611566, 2019). "It has, however, become clear that specialized CD4+ T-cell effector subsets with direct cytolytic capacity can be induced to target a number of viral infections, e.g. HIV, poliovirus and influenza in a granzyme B, perforin or FasL mediated manner." (PMID 31575882, 2019). "Cytotoxic CD4+ T cells have been well characterized in contexts of viral infections, where cytotoxic CD4+ T cells either utilize granzyme B and perforin or Fas–FasL interactions to mediate killing of infected cells." (PMID 29545791, 2018). "We found, after 8 days of viral infection, that in CD169-DTR mice, Tet-GP33+ CD8+ T cells are more highly activated than in WT mice, as determined with granzyme B (GzmB), CD43, PD-1 and Lag3." (PMID 27809306, 2016). "Although the rapid production of IFN-γ or granules by T cells is important in defense against virus infections, there seems to be few double IFN-γ+granzyme B+ or IFN-γ+perforin+ cells were visualized in each CD4+T-cell population analyzed." (PMID 25836633, 2015). "Cytotoxic CD8+ cells are the primary cell type that controls these viral infections, but chronic viral infections can also induce the generation of atypical cytotoxic CD4+ cells, which express granzyme B." (PMID 23776639, 2013). "As expected, the frequency of CD69+, CD25+, GzmB+, and CD317+ cells significantly increased at 3DPI and 6DPI compared with PBS-treated mice, demonstrating cellular activation and the initiation of effector functions in response to viral infection." (PMID 38814732, 2024). "Overall, these results indicate that the absence of PD-1 in aged mice has a specific effect on improving granzyme B production in CD8+ T cells during HMPV infection but no discernible clinical effect on the outcome of viral infection." (PMID 38015461, 2023). "Cytotoxic effector genes (GZMA, GZMB, ID2, and PLAC8) were enriched in Δ382 SARS-CoV-2 infected patients, coupled with high plasma levels of IFN-γ, TNF-α, and IL-2 during the acute phase of virus infection." (PMID 34716845, 2022). "Even highly cytotoxic GzmB can be essential to control viral infection without inducing apoptosis in infected cells." (PMID 34529743, 2021). "Two genes (GZMB & CCL8) were differentially expressed in all cases, 71 genes were differentially expressed in respiratory infections caused by other viral infections, and 24 genes were expressed in nonviral respiratory illnesses;." (PMID 35003208, 2021). "GZMB was the most highly upregulated gene in the bronchial lymph node in response to BRSV infection, indicating a close relationship between this gene and the response to viral infection." (PMID 34733317, 2021). "Similarly, pDCs express granzyme B, which mediates killing of CD4 T cell during viral infections like HIV." (PMID 31181776, 2019). "Because memory CD8+ T cells that trafficked into VacV-infected skin expressed high levels of granzyme B, we next tested whether memory CD8+ T cells required cytolytic function to provide protective immunity against the viral infection." (PMID 30875408, 2019).
viral infection (continued). "Second, PyV infection i.p. activated NK and γδ T cells to produce IFNγ as did PyVTu injection, but in contrast to PyVTu cells, the viral infection did not lead to high levels of granzyme-B production." (PMID 20523894, 2010). "Consistent with this idea, we found that wt or gzmB+Tc cells are not able to reduce viral titers if virus infection had progressed for 18 h (in contrast to infection for 3 h) prior to Tc cell addition." (PMID 19838298, 2009). "Notably, akin to effector CD8 T cells elicited by viral infections, CD8 T cells elicited by the mRNA vaccine differentiated into MPECs or SLECs that displayed traits of bonafide effector cells, expressed granzyme B and T-bet, and produced cytokines such as IFN-γ." (PMID 37796612, 2023). "Interestingly, significant changes were observed for the innate immune response to viral infection, with an enhanced NK and NKT cell frequency at day 4 and day 10 post-infection respectively and significantly increased NK and NKT Granzyme B production in the burn injury compared to the Sham." (PMID 28068397, 2017). "Surprisingly, also here only very few of these cells expressed granzyme B. Considering the immunopathology in BKVN grafts, as evidenced by histological damage and deteriorated graft function, this large TRM population appeared not capable to control the viral infection." (PMID 27723787, 2016).
influenza (80 papers, 2011 to 2025). An acute viral infection of the respiratory tract, occurring in isolated cases, in epidemics, or in pandemics; it is caused by serologically different strains of viruses (influenzaviruses) designated A, B, and C, has a 3-day incubation period, and usually lasts for 3 to 10 days. "Granzyme B levels have also been associated with protection against laboratory diagnosed influenza after vaccination of older adults." (PMID 31408963, 2019). "Granzyme B has been associated with clinical protection from influenza and is produced by both CD4+ and CD8+ T-cells." (PMID 28769922, 2017). "Type I interferons such as IFN-α signal through STAT2; STAT2-deficient mice exhibit significantly reduced GzmB expression in lung CD4 T cells following influenza infection, supporting the role of this pathway in generating CD4 CTL in vivo." (PMID 28167943, 2017). "BSH supplementation further increased LAIV-induced granzyme B production (day2) in NK cells compared to ASH and in the BSH group granzyme B levels appeared to be negatively associated with influenza RNA levels in nasal lavage fluid cells." (PMID 26820305, 2016). "Degranulation and extracellular release of granzyme B can also cause inflammation and extracellular granzyme B has been implicated in increasing the risk of serious illness in the elderly, including the risk of influenza induced cardiovascular complications." (PMID 23118984, 2012). "As measured by validated Granzyme B assays in vitro, higher levels of granzyme B, which is major constituent of cytotoxic T cells and natural killer cell granules, in elderly subjects were associated with protection from influenza illness up to 10 weeks post-vaccination." (PMID 40574849, 2025). "A recent study shed first light on this by showing that CMV seropositivity was associated with a decline in Granzyme B responses to influenza and may predict increased susceptibility to influenza in older adults." (PMID 28647908, 2017). "These cells play a crucial role in eliminating virally infected cells, where, for instance, GzmB production by CD8+ T cells was shown to predict the effectiveness of an influenza vaccine in older adults." (PMID 40124502, 2025). "Granzyme B, quantified in fresh cell lysates, has been suggested to be a useful marker of cytotoxic T-lymphocyte response and a reliable predictor of influenza illness among the vaccinated elderly population." (PMID 38543806, 2024). "IFN-γ and granzyme B are both stimulated by influenza vaccination, and IFN-γ and granzyme B levels are correlated." (PMID 38932313, 2024). "We found that aged Pdcd1−/− mice had improved CD8+ T cell granzyme B production during either HMPV or influenza infection." (PMID 38015461, 2023). "Low granzyme B production by influenza-specific cytolytic T lymphocytes (CTL) from elderly humans correlated with lower protection against influenza and has been considered a marker for optimal protective vaccine response in humans." (PMID 37528458, 2023). "Unlike the low baseline stimulation levels seen for the FLU-v antigens, higher levels of IFN-γ- and granzyme-B-producing cells responding to the influenza strains were already detected pre-vaccination in both groups." (PMID 36146606, 2022). "Granzyme B is enriched in the culture media of influenza stimulated pDCs, as observed in the secretome analysis." (PMID 35401570, 2022). "In contrast to the low background levels of responses to FLU-v antigens prior to vaccination, IFN-γ and granzyme B responses to the influenza strains were elevated before vaccination, thereby reducing the fold increase from pre- to post-vaccination." (PMID 36146606, 2022). "Two studies in elderly adults and in aged mice showed that granzyme B stimulation following influenza and SARS-CoV-2 (ChAdOx1 nCoV-19) booster vaccination, respectively, would provide an enhanced immune response by reactivating granzyme B CD8 T cell activity." (PMID 35893819, 2022).